IL3 (interleukin 3)
Diseases named in the same sentence as IL3 in open-access papers (continued):
Sharing a sentence is not in itself a finding about the gene and the disease.
cancer (continued). "For instance, the super-induction of IL-2 (and potential activation of natural killer cells) and stimulatory effects on bone marrow generation by activation of IL-3 and GM-CSF synthesis could be important in immune-compromised cancer patients." (PMID 29112154, 2017). "IL-3, c-Kit and IKKs are involved in pathogenesis of a number of malignancies." (PMID 25749030, 2015). "In addition to IFN-γ, several other cytokines (such as interleukin (IL)-1β, IL-3, and IL-12p70) also showed increased production in the co-culture of cancer cells and immune cells in the presence of trastuzumab." (PMID 24693969, 2014). "Therefore, the systemic immune response was suppressed by the overwhelming number of cancer cells even though macrophages were activated by IL-3." (PMID 23441198, 2013). "Notably, several factors that were increased more than 2-fold, including SCF-1, VEGF, osteopontin, MCP-2/3, IL-3, IL-12, and IFN-γ, have all been implicated in various aspects of cancer development, and thus represent a unique signature of the secretome of BTG3-depleted normal human fibroblasts." (PMID 33311481, 2020). "The resulting formulations, IL3-Exo-Imatinib and IL3-Exo-BCR-ABL siRNA demonstrated specific targeting ability against CML cells and effectively inhibited cancer cell growth both in vitro and in vivo." (PMID 39204374, 2024). "TECs also influence cancer growth and dissemination by secreting factors (e.g., IL3/6/8, FGF, PDGF, TGFβ) that directly trigger cancer cell proliferation and migration." (PMID 38453816, 2024). "To further explore the antilung cancer mechanism of ZSD, we conducted Human Signal Transduction Pathway Finder PCR Array and found that TRAIL, glypican, IL-3-mediated signaling, Arf6 and mTOR signaling, and PI3K/AKT signaling pathway were mainly enriched." (PMID 33777320, 2021). "As such, IL-3 or its specific receptor subunit CD123 has been investigated as therapeutic targets, especially in AML where CD123 expression on cancer cells correlates with reduced patient survival." (PMID 30769926, 2019). "Conversely, some genes that displayed anti-HIV activity are known to be involved in signaling, both in various cancers (CD164, TNFRSF10A/D, ZWINT, MT1X, IL3) and immune or T cell activation (GBP5, CD1A)." (PMID 25980612, 2015). "ROC curve analysis demonstrated high sensitivity and specificity for IL3 in distinguishing between primary cancers with and without bone metastases, sometimes reaching 100%." (PMID 39125732, 2024). "Finally, by considering the genes recapitulating IL-3 biological functions, we proposed a model, including IL-3Rα, SNAI1, ZEB1, VIM, CTNNB1, MMP2, SPRY2, and CD274, that remarkably discriminates cancer aggressiveness (AUC = 0.86 95% CI = 0.82–0.89)." (PMID 36010912, 2022). "Biological pathway analysis revealed the downregulated DEGs are mainly enriched in vitamin A and carotenoid metabolism, wnt signaling, cancer pathway, TLR4 signaling and tolerance, G13 signaling pathway, tryptophan metabolism, differentiation pathway, IL-3, IL-4 signaling pathway." (PMID 34960172, 2021). "In particular, growth-regulated protein (GRO), ENA-78/CXCL5, TIMP-2, and leptin were strongly up-regulated in malignant seroma, whereas IGFBP-1 (insulin-like factor binding protein-1), IL-3, IFN-γ, FGF-9 and IL-16 were down-regulated in malignant versus benign seroma fluid." (PMID 26361584, 2015).
cancer (continued). "Fragment of Interleukin 3 The interleukin-3 (IL-3) fragment, a native ligand for the interleukin-3 receptor α, is overexpressed on chronic myelogenous leukemia (CML) blasts relative to normal hematopoietic cells, making it a viable target for cancer drug delivery systems." (PMID 39204374, 2024). "IL-3 is not primarily involved in steady-state hematopoiesis but acts as an early-acting factor at inflammation sites, playing a role in autoimmune diseases, cancer, and infections." (PMID 39447666, 2024). "Pathway analysis of our gene array data identified five canonical signalling pathways dysregulated in cancer, namely, Insulin Receptor Signalling, Dolichol and Dolichyl Phosphate Biosynthesis, UDP-N-acetyl-D-glucosamine Biosynthesis II, Ceramide Biosynthesis, and IL-3 Signalling pathways." (PMID 31754384, 2019). "However, IL-3 could not reduce platelet transfusions in certain cancer patients and has not shown improvement in adherence to chemotherapy regimens." (PMID 38256942, 2024). "In order to further complement our conclusions, we ran MD simulations of SMO and its naturally occurring cancer mutants R6.32 to H6.32 and W7.55 to L7.55 based on the crystal structure of human SMO in the absence of the extracellular CRD and without a crystallization scaffold in IL3 (PDB 4JKV)." (PMID 30737406, 2019).
Hematologic Malignancies (7 papers, 2013 to 2025). "CD123 targeting represents an effective therapeutic option for BPDCN patients and tagraxofusp, a drug based on a genetically engineered diphtheria toxin fused with IL-3, has shown robust activity and BPDCN was the first IL-3Rα targeting agent approved for the treatment of a hematological malignancy." (PMID 31547472, 2019). "This combination (diphtheria toxin and IL-3) is named SL-401 (tagraxofusp) and has reached phase II clinical trials, with robust activity in the blastic plasmacytoid dendritic cell neoplasm (BPDCN) and other hematological malignancies." (PMID 30621282, 2019).
infectious disease (4 papers, 2018 to 2025). A disorder directly resulting from the presence and activity of a microbial, viral, or parasitic agent in humans. "Furthermore, they are also involved in immune response pathways (IL-5, IL-3, IL-2 signaling pathways, and B cell receptor signaling) and in controlling G1/S cell cycle, DNA damage response, and infectious diseases." (PMID 40287690, 2025). "Therefore, this study deepens the knowledge that IL-3 is a key mediator in inflammation and suggests that recombinant IL-3 or CD123 receptor agonists may have the potential as novel therapeutic agents during inflammatory or infectious diseases." (PMID 36911737, 2023). "These discoveries contribute to our understanding of the intricate regulatory mechanisms governing IL-3/STAT5 signaling, providing novel insights for the development of therapeutic interventions in inflammatory and infectious diseases." (PMID 38702781, 2024).
hematologic cancers (3 papers, 2017 to 2022). "These experiments yielded unequivocal results using NIH3T3 cell transformation assays, and of greater relevance to hematopoietic cancers, using the hematopoietic IL3-dependent cell line 32D." (PMID 35574218, 2022). "We found that factors known to promote bone loss in solid and hematologic cancers (IL-6, MCP-1 and IL-3) were significantly elevated serum from Gzmb-HBZ mice compared to WT mice, indicating HBZ-mediated changes in cytokine secretion may directly or indirectly accelerate bone loss in this model." (PMID 29050201, 2017). "Most of the drugs predicted using the DGIDb database are used in hematological cancers and disorders, in line with the findings of the MCODE enrichment analysis, showing the crucial role of platelet degranulation and Interleukin-3, Interleukin-5, and GM-CSF signaling." (PMID 33918694, 2021).
inflammation (3 papers, 2021 to 2025). Aberrant reaction of the microcirculation characterized by movement of fluid and leukocytes from the blood into extravascular tissues. "IL-5 shares receptor components with IL-3 and granulocyte–macrophage colony-stimulating factor (GM-CSF), and it is involved in preventing eosinophilic apoptosis during allergen-induced airway inflammation." (PMID 40563358, 2025). "These βc cytokines, including IL‐3, GM‐CSF, and IL‐5, play a substantial role in regulating a broad spectrum of inflammatory responses, both accelerating pathogen clearance and potentially contributing to the pathogenesis of chronic inflammation." (PMID 39697159, 2024).
neurodegenerative disease (3 papers, 2024). A disorder of the central nervous system characterized by gradual and progressive loss of neural tissue and neurologic function. "Interleukin‐3 (IL‐3) has been implicated in programming microglia to cluster and clear pathological aggregates in neurodegenerative disease." (PMID 39697159, 2024). "It has been previously reported that IL‐3 promotes the clustering of microglia expressing IL‐3Rα to clear pathological aggregates in neurodegenerative diseases." (PMID 39697159, 2024). "In the central nervous system (CNS), IL‐3 levels correlate with the pathology of neurodegenerative diseases." (PMID 39697159, 2024). "Nevertheless, in the future, we need to clarify whether IL‐3 can rescue the memory ability of PD mouse models and further explore its potential use in treating neurodegenerative diseases." (PMID 39225429, 2024). "While interleukin‐3 (IL‐3) has been reported to exert both protective and detrimental effects in neurodegenerative diseases, however, its role in α‐synuclein pathology remains unclear." (PMID 39225429, 2024). "As a pleiotropic cytokine, IL‐3 shows diverse effects in neurodegenerative diseases." (PMID 39225429, 2024).
adenocarcinoma (1 paper, 2025). A common cancer characterized by the presence of malignant glandular cells. "It is hypothesised that an increase in the abundance of Chryseobacterium in recurrent lung samples following the resection of early-stage adenocarcinoma is positively correlated with an upregulation of IL-2, IL-3, and IL-17 in the host transcriptome." (PMID 40357400, 2025).
psychiatric disorder (1 paper, 2025). A disorder characterized by behavioral and/or psychological abnormalities, often accompanied by physical symptoms. "Among them, Nrf2 is a core target that co‐occurs in all three diseases (MS, AD, and psychiatric disorders), while molecules such as IL‐3 (MS, AD), TGF‐β1 (MS, ALS), C1q (AD, ALS), CHI3L1 (MS, AD), and NMDAR (psychiatric disorders, HD) play a role in both diseases." (PMID 40859959, 2025).
IL3 also shares sentences with these, for which no sentence is quoted: rheumatoid arthritis (5 papers); Hodgkins lymphoma (4); bronchiolitis (3); chronic periodontitis (3); dementia (3); multiple myeloma (3); Thrombocytopenia (3); allergic rhinitis (2); amyotrophic lateral sclerosis (2); B-cell acute lymphoblastic leukemia (2); cardiovascular diseases (2); chronic lymphocytic leukemia (2); cutaneous T cell lymphoma (2); glioblastoma (2); hairy cell leukemia (2); hemorrhage (2); myelodysplastic syndrome (2); schistosomiasis (2); skin infection (2); acute respiratory distress syndrome (1); airway hyperresponsiveness (1); ampullary cancer (1); autoimmune encephalitis (1); B cell lymphoma (1); bacterial infections (1); benign gynecological tumors (1); biliary atresia (1); blastic plasmacytoid dendritic cell neoplasm (1); blood cancers (1); bone marrow failure (1).
A further 67 diseases each share a sentence with IL3 in 1 paper.